CXCL9 (C-X-C motif chemokine ligand 9)
Diseases named in the same sentence as CXCL9 in open-access papers (continued):
Sharing a sentence is not in itself a finding about the gene and the disease.
osteoporosis (4 papers, 2021 to 2025). A condition of reduced bone mass, with decreased cortical thickness and a decrease in the number and size of the trabeculae of cancellous bone (but normal chemical composition), resulting in increased fracture incidence. "For example, it has been demonstrated that blockage of CXCL9 via neutralizing antibodies prevented bone loss in WT mice with experimental osteoporosis." (PMID 40047894, 2025). "In addition, neutralizing CXCL9 in experimental osteoporosis prevented bone loss in mice by increasing bone formation as well as decreasing bone resorption." (PMID 40047894, 2025). "To identify mechanisms of SPTBN1 in osteoporosis, we explored pathways related to SPTBN1 by STRING website and found that SPTBN1 may associate with TGF-β/Smad3 and STAT1/Cxcl9 signaling pathways." (PMID 33816505, 2021). "Thus, SPTBN1 may regulate osteoblast by TGF-β/Smad3 and STAT1/Cxcl9 signaling pathways in osteoporosis." (PMID 33816505, 2021). "Besides, these results suggested that the effect of SPTBN1 in osteoporosis also might be mediated by the STAT1/Cxcl9 signaling pathway." (PMID 33816505, 2021). "Taken together, these results suggested that SPTBN1 suppressed primary osteoporosis by facilitating the proliferation, differentiation, and inhibition of apoptosis in osteoblasts via the TGF-β/Smad3 and STAT1/Cxcl9 pathways." (PMID 33816505, 2021). "The results showed that overexpression of SPTBN1 significantly suppresses the development of primary osteoporosis by modulating VEGF, TGF-β/Smad3, and STAT1/Cxcl9 signaling pathways." (PMID 33816505, 2021). "Therefore, SPTBN1 may suppress primary osteoporosis of osteoblasts through Smad3/TGF-β and STAT1/Cxcl-9 signaling pathways." (PMID 33816505, 2021).
ovarian tumor (4 papers, 2008 to 2023). "Enhancer of zeste homolog 2 (EZH2)-mediated histone H3K27me3 and DNMT1-mediated DNA methylation suppress the ovarian tumor production of Th1-inducing chemokine, CXCL9 and 10, and decrease TIL in TME." (PMID 36991099, 2023). "A recent study by Dangaj revealed that induced CCL5 and CXCL9 by macrophages could enhance the infiltration of immunoreactive CD8+ T cells into ovarian tumor and promote the overall survival of patients." (PMID 35359417, 2022).
prostate tumors (4 papers, 2020 to 2022). "In prostate tumors it was found out that there is strong positive correlation between CXCL9 and CD8 expression." (PMID 34367961, 2021). "Collectively, we show that Cxcl5, but not Cxcl9/10 from the stromal cells, is the major downstream effector of stromal Foxf2 in suppressing prostate tumor growth." (PMID 36369237, 2022). "However, we found that ARID1A loss did not reduce Cxcl9 and Cxcl10 expression in PCa cells treated with IFN-γ or TNF-α and mouse prostate tumors." (PMID 36435834, 2022).
schistosomiasis (4 papers, 2012 to 2025). An infectious disease caused by parasitic trematodes of the genus Schistosoma that colonize human blood vessels and release eggs that can cause granulomatous reactions leading to acute (swimmer's itch or acute schistosomiasis syndrome) or chronic disease. "In vitro, we demonstrated that CXCL9 and CXCL10 inhibited the expression of collagen, TGF-β and TIMP1 of hepatic non-parenchymal cells of mice infected with S. japonicum, while increased the gene expression of MMP9, suggesting that they played an anti-fibrosis role in the liver of schistosomiasis." (PMID 22905138, 2012). "Individuals from schistosomiasis-endemic regions exhibit higher levels of CXCL10 and CXCL9 compared to non-infected individuals." (PMID 41476985, 2025). "The results showed that CXCL9 and CXCL10, but not CXCL11 or CXCL4, significantly inhibited the gene expressions of Col1α1, Col3α1 and α-SMA, indicating the potential anti-fibrosis effect of CXCL9 and CXCL10 in schistosomiasis." (PMID 22905138, 2012). "After bio-function analysis, we focused on two chemokines CXCL9 and CXCL10, and showed that both of them can inhibit the expression of collagen in human HSCs line LX-2, liver non-parenchymal cells, and primary HSCs of schistosomiasis mice indicating the anti-fibrosis property." (PMID 22905138, 2012).
scleroderma (4 papers, 2020 to 2024). Scleroderma is a rare autoimmune connective tissue disorder characterized by abnormal hardening of the skin and, sometimes, other organs. "In a bleomycin-induced mouse model of scleroderma, with a shorter duration of bleomycin induction meant to simulate localized scleroderma/morphea, CXCL9 and CXCR3 knockout mice were protected from the development of fibrosis." (PMID 39337619, 2024). "We then performed correlation analysis comparing serum CXCL9 concentration at each time point to the patient’s Localized Scleroderma Assessment Tool (LoSCAT) activity index (LoSAI) score." (PMID 37471168, 2023).
acne (3 papers, 2014 to 2024). An inflammatory process of the sebaceous glands which is characterized by comedones, nodules, papules and/or pustules on the skin. "Similar results were observed in a cohort study, the CXCR3 ligands CXCL9, CXCL10, and CXCL11 were overexpressed in acne lesions." (PMID 38321132, 2024). "Similar findings were observed in the German cohort, since STAT1 a positive regulator of Th1 development was induced, and the CXCR3 ligands CXCL9, CXCL10 and CXCL11, were overexpressed in lesional acne skin." (PMID 25153527, 2014).
adenoma (3 papers, 2023 to 2025). A neoplasm arising from the epithelium. "CXCL9 followed a similar trend but was only significantly lower in adenocarcinomas in the paired analysis, where 59% of adenomas had higher CXCL9 expression (p = 0.027)." (PMID 40699620, 2025). "Act1 downregulation in macrophages activates STAT3 that promotes adenoma-adenocarcinoma transition via CXCL9/10-CXCR3-axis in CRC cells and PD-1/PD-L1-axis in CD8+ T cells." (PMID 36978108, 2023). "Taken together, our findings confirmed that Act1 downregulation in macrophages activates STAT3 to promote adenoma-adenocarcinoma transition via CXCL9/10-CXCR3-axis in CRC cells and immunosuppression via PD-l/PD-L1 axis in CD8+ T cells." (PMID 36978108, 2023). "Our results showed that Act1 downregulation in macrophages activates STAT3 to promote adenoma-adenocarcinoma transition via CXCL9/10-CXCR3-axis in CRC cells and immunosuppression via PD-1/PD-L1-axis in CD8+ T cells." (PMID 36978108, 2023). "Therefore, macrophage-specific Act1 knockdown modulated adenoma transition and CRC progression by orchestrating CXCL9/10-CXCR3 and PD1/PD-L1 axis to cross-talk with CRC cells and CD8+ T cells in the tumor microenvironment." (PMID 36978108, 2023). "Additionally, C-X-C Motif Chemokine Ligand 9 (CXCL9) was included based on high nCounter counts in a small adenoma sample set (data not shown), and IL6 was included based on literature studies." (PMID 38979413, 2024).
AIDS (3 papers, 2010 to 2023). A syndrome resulting from the acquired deficiency of cellular immunity caused by the human immunodeficiency virus (HIV). "Our previous study showed that CXCL9 and CXCL11 levels were significantly increased in primary HIV infection, which was correlated with viral load and AIDS progression." (PMID 34447368, 2021). "We detected higher levels of IL-2R, CXCL9, CXCL10, CCL2, and IL-6 (p = 0.001, 0.0003, 0.0002, 0.017, and 0.0005, respectively) in plasma of AIDS patients compared to healthy uninfected controls (data not shown)." (PMID 21125014, 2010).
Atherosclerotic lesion (3 papers, 2012 to 2022). A lesion associated with atherosclerosis, a multifactorial and multipart progressive disease manifested by the focal development within the arterial wall of lesions, that ranges from the development of a fatty streak, plaque progression, and plaque disruption. "CXCR3 receptor is activated by IFN-γ-inducible chemokines such as CXCL9, CXCL10 (IP-10), and CXCL11 (I-TAC), which are highly expressed in atherosclerotic lesions and play an important role in Th1-cell homing." (PMID 25873769, 2015).
autoimmune liver diseases (3 papers, 2016 to 2023). "Only in our subgroup of patients with cholestatic or autoimmune liver diseases did CXCL9 drop out, most likely due to the small sample size." (PMID 36982370, 2023). "In the subgroup of cholestatic/autoimmune liver disease, CXCL9 lacked significance between the two subgroups." (PMID 36982370, 2023).
B-cell lymphoma (3 papers, 2016 to 2025). "In Addition, IL‐12 and Th1‐derived IFN‐γ exerted antitumor effects through the inhibitory effects of endogenous CXCL9 and CXCL10 on tumor vasculature in human Burkitt's lymphoma 51 and in B‐cell lymphoma 52, respectively." (PMID 27726306, 2016).
Burkitt lymphoma (3 papers, 2016 to 2024). A rare form of malignant mature B-cell non-Hodgkin lymphoma. "CXCL9/MIG induces tumor necrosis and exerts an important effect on antitumor response in Burkitt's lymphoma." (PMID 27556503, 2016). "In xenograft models, CXCL9 and CXCL10 has been shown to inhibit Burkitt’s lymphoma tumours established in nude mice." (PMID 28588211, 2017).
cardiomyopathy (3 papers, 2019 to 2025). A disease of the heart muscle or myocardium proper. "CXCL9 was associated with progression of atherosclerosis and some types of cardiomyopathy." (PMID 31083544, 2019). "CXCL9 and its receptor, CXCR3, are associated with the progression of IHD and cardiomyopathy." (PMID 31083544, 2019). "In response to IL-27, gene expression of TBX21, EOMES, and CXCL9, which are activated downstream of STAT1, STAT3, and STAT5 phosphorylation, was lower in patients with cardiomyopathy (i.e., the G1 and G2 groups) than that in uninfected subjects." (PMID 34061845, 2021). "The gene expression of CXCL9, coding for MIG in monocytes, was also low in patients with cardiomyopathy, suggesting that IL-27/IL-27R and IL-7/IL-7R may be altered in other cell types." (PMID 34061845, 2021).
cerebral toxoplasmosis (3 papers, 2021 to 2022). Infections of the brain caused by the protozoan toxoplasma gondii that primarily arise in individuals with immunologic deficiency syndromes (see also aids-related opportunistic infections). "Indeed, CXCL9 is known to induce T-cell activation and recruitment into the brain during cerebral toxoplasmosis." (PMID 35027063, 2022).
cutaneous leishmaniasis (3 papers, 2019 to 2023). Leishmaniasis affecting the skin. "Ritter and Korber demonstrated the key role of MIG in the self-healing of localized cutaneous leishmaniasis, confirming that lesions exhibited a strong expression of Th1-associated chemokines, such as CCL2/MCP-1, CXCL9/MIG, and CXCL10/IP-10." (PMID 37242376, 2023). "and cutaneous leishmaniasis involves the production of multiple Th1-associated chemokines including CCL2, CCL7, CXCL9, and CXCL10." (PMID 34543348, 2021). "CXCL10 and CXCL9 were also identified as the most highly “induced” genes in comparing lesion transcript profiles with normal skin of patients with American cutaneous leishmaniasis, consistent with their roles in inflammatory cell recruitment." (PMID 31419223, 2019).
depression (3 papers, 2023 to 2025). "This analysis exhibited several cytokines and receptors, including IL10, CXCL9, and CXCR4, as key components in the relationship between depression and immunotherapy efficacy." (PMID 40761787, 2025).
epilepsy (3 papers, 2014 to 2024). A brain disorder characterized by episodes of abnormally increased neuronal discharge resulting in transient episodes of sensory or motor neurological dysfunction, or psychic dysfunction. "CXCL11 levels and VEGFA levels increased the risk of epilepsy, CXCL1 levels, CXCL9 levels, IL-6 levels, TRAIL levels, and VEGFA levels were associated with an increased risk of FE and TTNFSF14 levels, VEGFA levels were associated with an increased risk of GE." (PMID 39315097, 2024). "Secondly, various inflammatory mediators such as CXCL9, CXCL3, and IL-6 have been shown to be dysregulated in patients with drug-resistant epilepsy." (PMID 34497517, 2021).
gout (3 papers, 2016 to 2025). A condition characterized by painful swelling of the joints, which is caused by deposition of urate crystals. "Additionally, a meta-analysis of 23 pairs of CIPs from 2 independent datasets identified an association between increased gout risk and elevated levels of CXCL9 (MIG)." (PMID 40388724, 2025).
HCMV infection (3 papers, 2010 to 2025). "Consistent with our previous findings, HCMV infection upregulated host genes associated with immune clearance, including CXCL9–11 and encoding type I interferons (IFNA/B) (16, 40, –, 45)." (PMID 40980889, 2025). "In murine cytomegalovirus infection and in Toxoplasma gondii infection, early release of CCL3 and CCL4 from APCs is vital for the influx of NK cells into affected tissues, and these cells are an important source of IFN-γ, which induces macrophages and dendritic cells to secrete CXCL9 and CXCL10." (PMID 20828409, 2010).
hepatitis C (3 papers, 2023 to 2024). "But only the gene expression of SELL and CXCL9 have no significantly between control and hepatitis C-MASH cellular model." (PMID 39605886, 2024).
Hypofibrinogenemia (3 papers, 2020 to 2025). Decreased concentration of fibrinogen in the blood. "The correlation network analyses between the molecules evaluated in the present study show that, in the group of patients with hypofibrinogenemia, it was possible to observe a predominance of a chemoattractive profile, with correlations between chemokines CXCL-8, CXCL-9, CCL-2, and CXCL-10." (PMID 32973773, 2020).
injury (3 papers, 2008 to 2021). Damage inflicted on the body as the direct or indirect result of an external force, with or without disruption of structural continuity. "Very recently, the same group reported increased BAL levels of CXCL9 and CXCL10 in a prospective multicenter study during episodes of acute rejection and acute lung injury in the first year post-LTx, which form known risk factors for future CLAD development." (PMID 34122421, 2021). "In LPS-mediated acute lung injuries, ROS enhanced the pulmonary epithelial cells to secrete CXCL9, which increased B-cell transfer to bronchoalveolar fluid." (PMID 33330617, 2020). "CXCL10/IP-10 (IFNγ-inducible protein 10) and CXCL9/Mig (monokine induced by IFN-γ) are up-regulated in CS-induced lung injury and may attract T-cell recruitment to the lung." (PMID 19087279, 2008).
Insulin resistance (3 papers, 2011 to 2025). Increased resistance towards insulin, that is, diminished effectiveness of insulin in reducing blood glucose levels. "In future it has to be validated if the other most differentially regulated genes between both tissues such as: SGCD, LCE3D, EREG, NDP and CXCL9, FSTL3, PDZK1IP1 could be used as biomarkers related to insulin resistance of adipose or liver tissues respectively." (PMID 21978410, 2011).
kidney failure (3 papers, 2017 to 2025). An acute or chronic condition that is characterized by the inability of the kidneys to adequately filter the blood. "Fetal urine chemokines CCL2 (MCP-1), CXCL9 (MIG), and CCL4 (MIP-1β) were identified as predictive of postnatal kidney failure in fetuses with PUV from the discovery cohort." (PMID 39614902, 2025). "We used poly I:C to increase the hepatic concentration of CXCL9; however, poly I:C is not available for clinical use owing to its toxic side effects, including shock, renal failure, coagulopathies, and hypersensitivity reactions." (PMID 29088306, 2017).
leishmaniasis (3 papers, 2014 to 2024). Infectious disease that is transmitted through the bite of hematophagous female phlebotomine sand flies. "The identification of hub genes of recruited datasets suggested that TNF, SOCS3, JUN, TNFAIP3, and CXCL9 may serve as potential infection biomarkers and could deserve value as prognostic biomarkers for leishmaniasis." (PMID 38839916, 2024).
lymphopenia (3 papers, 2014 to 2023). Reduction in the number of lymphocytes. "We found a significant increase in plasma CXCL9 and CXCL10 at the peak of infection, which coincided with profound lymphopenia." (PMID 37616070, 2023).
microcephaly (3 papers, 2019 to 2022). A congenital or acquired developmental disorder in which the circumference of the head is smaller than normal for the person's age and sex. "We demonstrated that IFN-α, CXCL10, and CXCL9 levels were significantly higher in CSF samples obtained from ZIKV-induced microcephaly cases, compared to healthy control subjects." (PMID 31474994, 2019). "Interestingly, consistent with the in vitro results, two CXC chemokine ligands were found at significantly higher levels in the CSF samples from microcephaly cases: CXCL9 and CXCL10 (p = 0.028, and p = 0.0003, respectively)." (PMID 31474994, 2019). "From ZIKV-confirmed infant microcephaly cases, we detected a similar profile characterized by the presence of IFN-α, CXCL10, and CXCL9 in cerebrospinal fluid (CSF) samples collected after birth, evidencing a sustained CNS inflammation." (PMID 31474994, 2019).
myocardial infarction (3 papers, 2019 to 2024). Gross necrosis of the myocardium, as a result of interruption of the blood supply to the area, as in coronary thrombosis. "This study was aimed to investigate the effects of CXCL9/CCL20 on cardiac fibrosis following myocardial infarction (MI)." (PMID 31083544, 2019).
neuropathy (3 papers, 2023 to 2025). A disorder affecting the nervous system that manifests with pain, tingling, numbness, and/or muscle weakness. "However, long-lasting changes (until Day 28) were observed only for CXCL9, suggesting that this chemokine is responsible for persistent neuropathy." (PMID 37570736, 2023). "Therefore, CXCL9 appears to be a very important nociceptive mediator in neuropathy and is particularly crucial for the persistence of neuropathy." (PMID 37570736, 2023). "Plasma levels of CXCL9, CXCL10, and CXCL11 have been measured in patients with neuropathy." (PMID 41302503, 2025).
oral cancer (3 papers, 2017 to 2025). "In our study examining the impact of cytokines on oral cancer, we observed findings regarding CXCL9 and TRANCE that differ from their roles in previous study." (PMID 40489865, 2025). "TERF2 downregulates CXCL9 expression in oral carcinoma cell lines." (PMID 39328506, 2024). "The production of CXCL9/10/11 chemokines in oral cancer cells is also novel." (PMID 28253295, 2017).
osteomyelitis (3 papers, 2022 to 2024). An acute or chronic inflammation of the bone and its structures due to infection with pyogenic bacteria. "To test the protective role of CXCL9/10 in an early stage of S. aureus osteomyelitis in mice, we administrated recombinant CXCL9 or CXCL10 to 10-month-old mice with S. aureus osteomyelitis." (PMID 39001897, 2024). "In this study, we uncovered a previously uncharacterized role of monocyte-originated CXCL9/10 in regulation of bactericidal function of neutrophils and macrophages in vitro and at an acute stage of S. aureus osteomyelitis in mice." (PMID 39001897, 2024). "To determine whether enhanced production of CXCL9/10 in monocytes from young mice might account for increased bactericidal function in neutrophils and macrophages, we applied AMG487 to 8-week-old mice with S. aureus osteomyelitis." (PMID 39001897, 2024).